STAT3 (signal transducer and activator of transcription 3)
Diseases named in the same sentence as STAT3 in open-access papers (continued):
Sharing a sentence is not in itself a finding about the gene and the disease.
tumor (continued). "Median tumor onset was 294 days in Myc Stat3 CKO mice and 360 days in Myc mice with Stat3." (PMID 27589562, 2016). "Also other JAK2/STAT3 inhibitors have been tested, including AZD1480, which resulted in low levels of MDSCs in tumor bearing AZD1480 treated mice." (PMID 27029037, 2016). "Moreover, compared with STAT3 group and CDDP group, tumour volume in the combination group decreased more significantly (P<0.05)." (PMID 27129294, 2016). "Moreover, through activation of NF-κB and STAT3, TNF-α can enhance epithelial-mesenchymal transition which are critical steps that allow polarized epithelial tumor cells to become mesenchymal like, enhancing cell migration and invasion." (PMID 27323816, 2016). "In cancer cells, GRIM-19 expression was actually down- regulated in cancer cells, and its level was inversely correlated with phosphorylation level of STAT3, suggesting that a lower GRIM-19 level favors or promotes tumor growth via promoting STAT3 biological activity." (PMID 27101310, 2016). "An activated STAT3 mutant upregulated VEGF expression and promoted tumor angiogenesis." (PMID 26956882, 2016). "We also observed a complete lack of phospho-STAT3 staining in CADM1-expressing SqCC tumour xenografts (red)." (PMID 27035095, 2016). "In HCC, elevated miR-155 has been shown to target suppressor of cytokine signaling 1 (SOCS1), thereby activating signal transducer and activator of transcription 3 (STAT3) signaling and enhancing the expression of MMP9, which results in increased tumor invasiveness." (PMID 26950158, 2016). "In multivariate survival analysis, only high ph-STAT3 tumour cell expression was a predictor of improved CSS (P=0.010) independent of other tumour and host-based factors." (PMID 27769057, 2016). "Thus, by promoting STAT3 activation, repression of PIAS3 expression in tumor cells can indirectly contribute to NK cell dysfunction by altering the cytokine profile of the cancer." (PMID 27148255, 2016). "Taken together, these data showed that STAT1 reduced SLUG expression and mediated the OSM-dependent suppression of cell motility in vitro and tumor metastasis in vivo, while STAT3 did not interfere with this effect even though it was phosphorylated." (PMID 27486982, 2016). "In contrast, 95 kDa phospho-STAT5 levels were higher in tumours initiated from SH-4-54-resistant clones, while phospho-STAT3 levels did not change when normalized to levels of total STAT3." (PMID 27513743, 2016). "However, the fact that OSM induces the phosphorylation and activation of both STAT1 and STAT3 and yet still presented anti-tumor effects poses a paradox why LAC cells selectively response to activated STAT1 and ignore the pro-oncogenic STAT3." (PMID 27486982, 2016). "However, both SSM2 and SSM3 tumor cells also express the activated forms of JAK2 and STAT3 in SHAM-operated mice." (PMID 27391074, 2016). "Although antibody depletion experiments showed that T cells played a critical role in tumor rejection, NK cells were also involved, as NK depletion using anti-asialo-GM1 antibodies partially abrogated the effects of a STAT3 small molecule inhibitor (CPA-7) on rejection of MB49 tumors." (PMID 27148255, 2016). "The link of high glucose and STAT3 activation was confirmed in tumor tissues from CCA patients with DM that exhibited higher STAT3 activation than those without DM." (PMID 26743134, 2016). "Constitutively activated STAT3 is observed in the majority of HCC but not in normal liver nor adjacent non-tumor tissue." (PMID 27102295, 2016). "We then enriched liver TICs by flow cytometer using anti-CD133 antibody, and silenced Stat3 or Sox4 in liver TICs and non-TICs using pSiCoR lentivirus, followed by sphere formation and tumour initiation assays." (PMID 27553854, 2016).
tumor (continued). "We also evaluated the correlation between STAT3 overexpression and the TNM stage of tumor." (PMID 26959884, 2016). "Microarray analysis of the tumors revealed that targeting STAT3 increased the expression of multiple chemokines, such as CCL2, CCL9, CCL12, CCL17, and CCL21c, and induced downregulation of MHC class I molecules H2-D1 and H2-K1 in the tumor cells." (PMID 27148255, 2016). "Using tumour xenograft studies, we demonstrate that the extracellular domain of CADM1 regulates SqCC progression via generation of a HER2-ITGα6β4-CADM1 complex at the cell surface that inhibits HER2-ITGα6β4 mediated STAT3 phosphorylation." (PMID 27035095, 2016). "Of note, we observed that fractionated radiation increased the secretion of IL-6 in the tumor microenvironment through the activation of the JAK/STAT3/Notch2 signaling pathway as shown in a schematic model." (PMID 27462787, 2016). "Intriguingly, however, 14,15-EET could induce neutrophilic infiltration in metastatic lesions by activating STAT3 and JNK pathways to induce the expression of IL-8 and CXCL15 in tumor cells." (PMID 27270316, 2016). "The respective median survival was augmented by at least 18 months in comparison to patients with tumor specimens showing either only IL-6Rα or nuclear STAT3 or neither of the two." (PMID 27191495, 2016). "Tumor tissue from mice injected with GBM cells with enforced miR203 expression had lower protein levels of miR203 targets (STAT1, PI3KCA and IVNS1ABP), but the levels of STAT3 and actin were unaffected." (PMID 27705947, 2016). "However, data from orthotopic tumours derived from implantation of 4T1 cells into mice suggest that the relationship between mCLCA5 and Stat3 activity may be complex, with separate populations of cells expressing high levels of mCLCA5 or transcriptionally active (nuclear) Stat3." (PMID 27711075, 2016). "Without Stat3, these tumorigenic cells are able to continuously grow, resulting in the accelerated tumor detection that we described." (PMID 27589562, 2016). "Moreover, activated JAK2/STAT3 increases AKT activation through the induction of AKT, while increased STAT3 and AKT activation leads to tumor development and EMT." (PMID 26515594, 2015). "Our results suggest that the miR-21/CDK5 axis could partially mediate tumor cell mobility and EMT by targeting STAT3 in HNSCC." (PMID 26690371, 2015). "Furthermore, these cells have increased exposure to the factors necessary for tumor relapse, including CXCL12, through its receptors CXCR4 and CXCR7, IL6 through the Jak2/Stat3 pathway, EGF, FGF and IGF, among others." (PMID 25797268, 2015). "Despite the fact that Stat3-deficient tumours had a growth advantage, they did not progress to become more invasive than Stat3-proficient tumours or metastatic." (PMID 25734337, 2015). "Tumor growth is suppressed in IL-17 knockout mice and IL-17/IFN-γ double-knockout mice, and a mechanism for this knockout is that IL-17 induces the production of IL-6 by tumor cells, which in turn promotes tumor growth through a STAT3–dependent pathway." (PMID 25992978, 2015). "Cixutumumab-treated tumours of STAT3 shRNA-transfected MDA231–Luc cells showed significant decreases in levels of IGF-2 expression, F4/80+ macrophages (left) and CD34+ VE cells (right) when compared with control tumours." (PMID 26465273, 2015). "Although the function of EZH2 is still unclear, recent research revealed that phosphorylation of EZH2 at serine 21 (pS21 EZH2) by AKT facilitates STAT3 methylation by EZH2 and enhances STAT3 activity, which is necessary to maintain GBM stem-like cell self-renewal and tumor malignancy." (PMID 25823657, 2015). "Constitutive STAT3 activation promote VEGF-A expression and stimulates tumor angiogenesis." (PMID 25596740, 2015).
tumor (continued). "For spleens from tumor bearing old mice majority of the upstream regulators are either interferons (IFNγ, IFNα, IRF3, IRF7, and IFNA2) or are related to the immune system (IKBKB, CHUK, NFκB, NFκBIA, STAT3, and mir-21) and are predicted to be up-regulated." (PMID 26497558, 2015). "As IL-6/STAT3 signaling can promote proliferation and survival of NSCLC cells, these data suggest that NOX4-induced IL-6 expression, at least partly, accounts for its tumor-promoting effect." (PMID 25504436, 2015). "It is reported that Slit2, as a potent lymphangiogenic factor, contributes to tumor lymphatic metastasis; VEGF-A treated lymphatic endothelial cell exhibited STAT3 activation in the nucleus, thereby enhancing lymphatic endothelial cell migration and increased tube formation." (PMID 26187792, 2015). "Although RKIP can block Stat3 activity, it is unknown whether Stat3 mediates RKIP-regulating tumor cell invasion and metastasis." (PMID 25915430, 2015). "They appear to play opposite roles in tumourigenesis: STAT3 is considered an oncogene because it promotes cell survival/proliferation, while STAT1 enhances inflammation and immunity, triggering anti-proliferative and pro-apoptotic responses in tumour cells." (PMID 25705130, 2015). "We found that JSI-124 (1 mg/kg/day) significantly suppressed tumor volume and tumor weight without any side effects on mice, and remarkably reduced neovascularization accompanied by down-regulation expression of p-STAT3 and p-VEGFR2." (PMID 25789853, 2015). "Our assays suggest an additional benefit of inhibiting the STAT3/IDO1 axis in resistant cells, i.e. the restoration of a significant expansion of T-lymphocytes that would be otherwise suppressed in the presence of multidrug resistant tumor cells." (PMID 25955018, 2015). "The activation of STAT3 results in expression of many target genes including matrix metalloproteinases (MMPs), cyclooxygenase-2 (COX-2) and angiopoietin-2 (Ang-2) which are required for tumor cell migration, angiogenesis as well as metastasis." (PMID 26575424, 2015). "Silencing of STAT3 with two different shRNAs (clones #1 and #2, respectively) or pharmacological inhibitors (Sta-21 and Stat3 Inhibitor XIII) produced a significant decrease in the number and in the size of LCSs generated by NSCLC cells and impaired tumor growth in mice (n = 5/group)." (PMID 26486080, 2015). "Moreover, the role of STAT3 in angiogenesis was reported by its actions in increasing VEGF expression in cardiac myocytes and tumor settings." (PMID 26514658, 2015). "Blocking the STAT3 activation by WP1066 effectively abrogated IL-6-induced Jagged-1 expression, strongly inhibited the growth of the trastuzumab resistant cells, and enhanced the anti-tumor activities of trastuzumab in the resistant cells." (PMID 25669984, 2015). "Given that our work now positions STAT3 as an immediate upstream regulator of HIF, drug targeting of STAT3 may be an alternative therapeutic strategy for the treatment of vascularized tumours." (PMID 26697523, 2015). "Although trametinib-treated AsPC-1(Vector) xenografts (V + T) impaired tumor growth, its effect was not stronger than in AsPC-1(STAT3-shRNA) xenografts (S + T) mice." (PMID 25961376, 2015). "More interestingly, several STAT3-regulated proteins important for tumor cell growth and apoptosis, such as CDK2, cyclin A or caspase 3, exhibited a down-regulated expression and cleaved activation respectively in STAT3-knockdown U266 cells." (PMID 25865044, 2015). "In addition, immunoblot analysis revealed that the phosphorylation levels of STAT3, MAPK and AKT were significantly lower in SKBR3 xenograft tumours from mice treated with LDFI-PEG than in tumours from vehicle-treated controls." (PMID 25721149, 2015). "Activated STAT3 leads to transcription of various target genes, such as cyclin D1, Bcl-2, Bcl-xL, matrix metalloproteinase 2 (MMP2), and VEGF, to regulate cell survival, angiogenesis, immune evasion, and inflammation in tumor microenvironment." (PMID 25789853, 2015).
tumor (continued). "Bcl-2 inhibitors, STAT3 inhibitors, and therapeutic strategies modulating BCR signaling, tumor microenvironment and cytokine/chemokine axes may help in the management of CD5+ DLBCL patients." (PMID 25760242, 2015). "Moreover, compared with the normal thymic tissue, TET demonstrated higher expression of c-Jun and STAT3 and progressive TET harboring higher tumor stages exhibited higher expression of c-Jun and STAT3." (PMID 25866678, 2015). "Moreover, cooperation between the Stat3 and AKT signaling pathways results in tumor development and EMT in the prostates of mice." (PMID 26515594, 2015). "STAT3 has been shown to activate ANGPTL4 directly or indirectly through transcriptional regulation of VEGF and HIF-1 in various human cancers, so we next examined the relationship of STAT3 and ANGPTL4 expression in GBM to tumor grade and patient survival." (PMID 25955030, 2015). "Because many types of cancer cells express STAT3 and EMT is a typical phenomenon upon metastatic stimuli, such as growth factor, Lycorine may have functions in inhibiting other tumor metastasis via the same mechanism that revealed in our research." (PMID 25915156, 2015). "Furthermore, the Bcl2 family is regulated mainly by the JAK/STAT3 and ERK pathways in certain tumor cells." (PMID 25373392, 2015). "Unexpectedly, while both tumor and muscle expressed comparably abundant amounts of STAT3, phosphorylation (reflective of activation) was present in the muscle but not in the tumor." (PMID 25861239, 2015). "Inactivation of NF-κB, STAT3, or HIF-1α, neutralization of CCL2 or CXCL12, or TAM depletion results in disrupted angiogenesis and decreased tumor growth, highlighting the critical role of inflammatory mediators in tumor angiogenesis." (PMID 26501341, 2015). "Thus, the combination of STAT3 inhibitor AG490 and enzalutamide significantly inhibited tumor growth and induced cell apoptosis." (PMID 28031890, 2015). "While no appreciable differences were observed in the activation of Akt, MAPK or STAT3 in the tumor lysates between genotypes (data not shown), several components of the NF-κB pathway were modified in MMTV-RonHGFL−/− tumors." (PMID 25938541, 2015). "STAT3 is involved in RCC carcinogenesis, growth and tumor angiogenesis." (PMID 28031890, 2015). "Multiple signaling pathways such as the mitogen-activated protein kinase/extracellular signal-regulated kinases (ERK), signal transducer and activator of transcription 3 (STAT3), and Akt/mammalian target of rapamycin (mTOR) pathways are involved in tumor biology." (PMID 25965999, 2015). "Taken together, these results suggest that elevated levels of IL-21 in the tumors of Apcmin/+ mice support a tumor-promoting inflammatory microenvironment characterized by enhanced production of IL-17A, IL-22, TNF-α and IL-6 and hyper-activation of STAT3/NF-kB." (PMID 25839161, 2015). "Moreover, in murine RCC xenografts, axitinib augments CD8+ T cell-mediated antitumor activity against renal carcinoma via a STAT3-dependent reversal of myeloid suppressor cells (MDSC) accumulation in the spleens and tumor beds." (PMID 26474283, 2015). "Both STAT3 and STAT1 also regulate tumour angiogenesis and metastasis, albeit in opposite ways." (PMID 25880691, 2015). "Nonetheless we were encouraged by reports of selective STAT3 blockade using small interfering RNA (siRNA) and small hairpin RNAs (shRNA) and by pharmacologic agents such as WP1066, that have inhibited GBM cell proliferation in vitro and tumor growth in vivo." (PMID 26283544, 2015). "Nude mice were injected intravenously with AGS cells treated with anti-Fas or treated with STAT3 inhibitor without anti-Fas; tumor pulmonary metastases were measured." (PMID 25992623, 2015). "Also, it indicated that the debulking effect of STAT3 inhibition in mice HNSCC model was rather a comprehensive effect on CSCs, proliferation, angiogenesis and tumor infiltrating immune cells." (PMID 26556875, 2015).
tumor (continued). "STAT3 promotes cell survival, proliferation, motility, immune tolerance and is considered as an oncogene, while STAT1 enhances inflammation, innate and adaptive immunity and triggers antiproliferative and proapoptotic responses in tumor cells." (PMID 26551008, 2015). "Here we have demonstrated that IL-1RT1−/− signaling is not required for IL-11/STAT3 mediated pathology, with genetic depletion of IL-1RT1−/− resulting in a more severe tumor phenotype by promoting an anti-inflammatory, pro-tumorigenic environment." (PMID 25528766, 2015). "However, STAT3 is also vital for the maintenance of normal stem cells and is a critical component of normal immune responses; therefore, targeting STAT3 will not be specific to tumor cells and may cause major side effects." (PMID 26258069, 2015). "While inhibiting a single pathway including EGFR and JAK/STAT3 was not sufficient to significantly block cell growth and survival, dual blockade of STAT3 and EGFR resulted in simultaneous attenuations of multiple survival pathways and dramatically increased anti-tumor activity in vitro and in vivo." (PMID 25928246, 2015). "STAT3 acetylation was detected in IDO-positive, as well as IDO-negative tumor cells." (PMID 24657910, 2014). "Here we report, garcinol, a polyisoprenylated benzophenone, could suppress STAT3 activation in HCC cell lines and in xenografted tumor of HCC in nude mice model." (PMID 24655440, 2014). "The results of the present study revealed that activated STAT-3 stimulated the injured liver cells to secrete VEGF and IL-10 to affect the differentiation and maturation of DCs, and thereby inhibited the immune response, allowing the tumor cells to escape it." (PMID 25009646, 2014). "In addition, we have proposed three other genes, E-cadherin, Stat3, and MMP-9, as prognosis biomarkers of tumor metastasis." (PMID 24647137, 2014). "STAT-3 is a transcription factor responsive to a variety of cytokines and growth factors via the JAK-STAT signal transduction pathway, which is important in tumor invasion, metastasis, angiogenesis and tumor immune escape." (PMID 25009646, 2014). "One of the responsible mechanisms for induction of tumor growth could be the activation of IL6–JAK1–signal transducer and activator of transcription 3 (STAT3) axis by US28 in vitro and in vivo." (PMID 25202681, 2014). "While we are convinced that the anti-angiogenic effect we observe with the STAT3 decoy is not solely due to its inhibition of STAT3, the agent is nonetheless effective at inhibiting tubule formation in vitro and in decreasing tumor angiogenesis in vivo." (PMID 24404126, 2014). "To explore the interdependence of molecular signaling events initiated by endothelial cells on tumor cells, we exposed HeLa to HDMEC CM in the presence of chemical inhibitors of STAT3, Akt, or ERK pathways and analyzed the interdependency of the phosphorylation events." (PMID 24533454, 2014). "Previous studies have hypothesized that the STAT3 and PI3K/Akt signaling transduction pathway has an important role in tumor cells." (PMID 25009620, 2014). "However, in epithelial cell lines, miR-21 is activated by IL-6 and STAT3 and targets PTEN, which leads to increased NF-κB activity and tumour growth." (PMID 25598707, 2014). "This led to a suppression of tumor cell growth, a decreased colony formation and an induction of apoptosis, but spared normal cells or cancer cells lacking constitutively active STAT3." (PMID 25268165, 2014). "Furthermore, a transcription factor, signal transducer and activator of transcription 3 (STAT3), was revealed to mediate the tumor-promoting function of PKR in HepG2 cells, as shown by in vitro cellular proliferation and migration assays." (PMID 25360179, 2014). "The presence of stalled lesions or occult tumors indicate that proliferation is being constrained by tumor suppressive senescence, which may include JAK/STAT3 signaling." (PMID 24675570, 2014).